FAT1 (FAT atypical cadherin 1)
Diseases named in the same sentence as FAT1 in open-access papers (continued):
Sharing a sentence is not in itself a finding about the gene and the disease.
glioma (19 papers, 2017 to 2025). A benign or malignant brain and spinal cord tumor that arises from glial cells (astrocytes, oligodendrocytes, ependymal cells). "In contrast to findings in glioma, FAT1 expression in T-ALL was positively linked to WNT target gene expression not fitting the model of a negative β-Catenin regulator." (PMID 36653435, 2023). "Thus, FAT1 possibly contributes to glioma-associated immunosuppression via MDSCs as well, although the exact molecular mechanism involved during the interplay of tumor cells and MDSCs remains to be studied in detail." (PMID 35720420, 2022). "Links between FAT1 and immunosuppression have been documented in glioma where high FAT1 expression drives TGF-β1 production 59 while another study in non-small cell lung cancer reached similar conclusions." (PMID 40083689, 2025). "FAT1 has shown oncogenic effect in glioma by down-regulating the tumour suppressor gene PDCD4, which leads to activation of AP1 Transcriptional activity thereby increasing the EMT and inflammatory microenvironment of tumour Cells." (PMID 37476290, 2023). "Our preliminary TIMER2.0 analysis in TCGA data revealed an inverse correlation between FAT1 expression and infiltration levels of tumor-inhibiting immune cells in glioma, cervical cancer, liver cancer, and pancreatic cancer." (PMID 35720420, 2022). "FAT1 knockdown in U87MG/A172 maintained in severe hypoxia primary glioma cultures led to significant reduction of EMT/stemness markers as compared to the controls, suggesting FAT1 is a regulator of EMT/stemness in hypoxic GBM." (PMID 35965328, 2022). "Reduced TGF-β1 expression was also observed in THP-1 cultured in conditioned media from FAT1-depleted glioma cells, thus contributing to immune suppression." (PMID 35720420, 2022). "To study the potential involvement of MDSCs in FAT1-mediated immunosuppression in tumors, we studied the expression of surrogate markers of MDSCs, namely, PD-L1, PD-L2, and IL-10 in gliomas." (PMID 35720420, 2022). "This indicates some secretory product in high FAT1-expressing glioma cell supernatant that affects the polarization of THP-1 cells." (PMID 35720420, 2022). "In experiments using glioma cells and immortalized human brain astrocytes, they found that knockdown of FAT1 resulted in a decrease in plasma membrane β-catenin staining, and a significant increase in nuclear β-catenin translocation." (PMID 35965328, 2022). "We also checked for modulation of the TGF-β1/2 expression in response to FAT1 knockdown in representative cell lines of glioma and other cancers such as U87MG (GBM), HeLa (cervical cancer), Panc-1 (pancreatic cancer), and HepG2 (hepatocellular cancer)." (PMID 35720420, 2022). "Our ELISA results showed decreased secretion of IL-6 from glioma cells in response to FAT1 knockdown." (PMID 35720420, 2022). "This possibly indicates polarization changes in monocytes in the presence of FAT1-expressing glioma cells." (PMID 35720420, 2022). "Our lab has previously reported the oncogenic role of FAT1 in glioma via regulation of migration, invasion, and stemness." (PMID 35720420, 2022). "Following the patient sample study, we transiently silenced FAT1 gene in various in vitro cancer cell lines and primary cultures of surgical gliomas." (PMID 35720420, 2022). "The deletion of Fat1 signaling reduce glioma cells migration and invasiveness, an effect that was related to an increase of the expression of tumor-suppressor gene programmed cell death 4 (PDCD4)." (PMID 35269788, 2022). "In glioma cells a high expression of Fat1 dependent on the activation of NFκB signaling was observed." (PMID 35269788, 2022). "We noted a positive association between FAT1 expression and expression of TGF-β1/TGF-β2 in glioma and cancers of the liver, cervix, pancreas, and colon in these databases." (PMID 35720420, 2022). "TGF-β1 was observed to be significantly correlated with FAT1 expression in GLASS glioma tumors (n = 102; r = 0.352, p = 0.0001)." (PMID 35720420, 2022).
glioma (continued). "In the present study, we have found an oncogenic role of FAT1 via modulation of immunosuppression using primary cultures derived from surgical gliomas and the U87MG cell line." (PMID 35720420, 2022). "We also noted decreased secretion of TGF-β1 in response to FAT1 knockdown in case of siFAT1-treated cultures of glioma cells, HeLa cells, and HepG2 cells using an ELISA array." (PMID 35720420, 2022). "While cancers of skin, lung, head and neck, and mouth display a tumor-suppressive function of FAT1, other cancers such as hepatocellular carcinoma, cervical cancer, pancreatic cancer, and gliomas are known to show an oncogenic role of FAT1." (PMID 35720420, 2022). "In mRNAseq_693 dataset of CGGA, FAT1 expression was observed to be positively correlated with TGF-β2 expression in primary glioma cases (r = 0.344, p < 0.01) and recurrent glioma cases (r = 0.447, p < 0.01)." (PMID 35720420, 2022). "Our lab has reported FAT1 as a crucial regulator of glioma cell migration and invasiveness via upregulation of EMT genes like, Snail, Vimentin, LOX and N-cadherin." (PMID 33878524, 2021). "Interesting parallels between the activity of NFкB and FAT1 have been demonstrated, at least in glioma." (PMID 31992226, 2020). "Similar observation of positive expression correlation between NFкB (RelA) and FAT1 in other non-glioma tumors like pancreatic, hepatocellular, stomach and lung tumors suggests the significance of NFкB (RelA)-FAT1 link in other tumors as well." (PMID 31992226, 2020). "We had initially demonstrated that FAT1 is a major contributor to pro-tumorigenic inflammation in gliomas driving the upregulation of pro-inflammatory cytokines like IL6 and IL1ß and also COX2 via AP1 activation." (PMID 31992226, 2020). "The prevalent mutation characterized in GBM is homozygous deletion of FAT atypical cadherin 1 (FAT1), which initiates the upregulation of Wnt signaling in glioma." (PMID 31684152, 2019). "One study reports that the expression of FAT1 is positively correlated with that of TGFβ1/2 in human gliomas, primary glioma cultures, and other cancer cell lines (U87MG, HepG2, Panc-1, and HeLa cells), and that FAT1 silencing results in decreased expression and secretion of TGFβ1/226." (PMID 38782965, 2024). "Targeting STAT1 through FDA approved drugs could possibly rescue the oncogenic effect of FAT1 in glioma mediated by FAT1 -PDCD4 axis." (PMID 37476290, 2023). "FAT1 expression was also observed to correlate positively with the expression of surrogate markers of MDSCs [programmed death ligand-1 (PD-L1), PD-L2, and interleukin (IL)-10] in glioma tumors, suggesting a potential role of FAT1 in MDSC-mediated immunosuppression." (PMID 35720420, 2022). "Hence, it is possible that in a heterotypic tumor microenvironment, especially in glioma, FAT1 influences TGF-β expression in more than one cell type, thereby contributing to an immunosuppressive milieu." (PMID 35720420, 2022). "High- or medium-intensity staining was observed in the tumor tissues of glioma, head and neck, thyroid, colorectal, endometrial, liver, urothelial, lung, pancreatic cancers, and lymphomas, indicating that the FAT1 protein was significantly overexpressed in the tumor tissues of these diseases." (PMID 36517565, 2022). "Our results indicate a potential role of FAT1 in promoting an immunosuppressive microenvironment in gliomas, which might extend to other cancers as well." (PMID 35720420, 2022). "According to this, it is possible to propose that in the tumoral hypoxic microenvironment, an increase of Fat1 signaling in astrocytes and glioma cells contributing to tumoral migration and tumoral angiogenesis through HIF-1 signaling conduiting to an aggressive tumor pattern." (PMID 35269788, 2022). "Hence, upregulated FAT1 in tumor cells positively correlates with increased presence of MDSCs in glioma tumors as indicated by the expression of MDSC surrogate markers." (PMID 35720420, 2022).
glioma (continued). "In addition, we also explored the potential involvement of MDSCs in FAT1-mediated immunosuppression in gliomas." (PMID 35720420, 2022). "Thus, FAT1 depletion in patient-derived glioma cells results in a downregulated mRNA expression of TGF-β1 and TGF-β2, which is reflected by decreased Serpine1 expression as well." (PMID 35720420, 2022). "Similarly, FAT1 was found to promote stemness and clonogenicity in glioma cells by regulation of stemness markers, such as SOX2, OCT4, Nestin and REST." (PMID 33878524, 2021). "Hence, accumulating evidence points to an important role of FAT1 in regulating various signaling pathways that operate during glioma pathogenesis." (PMID 33878524, 2021). "In many cancers including glioma, FAT1 is known to increase migration and invasion of tumor cells." (PMID 31992226, 2020). "FAT1 expression is found to be upregulated in different cancers like pancreatic cancer, hepatocellular carcinoma, B-cell acute lymphoblastic leukemia, colon cancer and glioma suggesting its oncogenic function in these cancers." (PMID 31992226, 2020). "The clonogenic effect of FAT1 has also been reported in U251 glioma cells." (PMID 31992226, 2020). "In addition to glioma, positive correlation between NFкB (RelA) and FAT1 expression was also observed in other tumors like pancreatic, hepatocellular, lung and stomach cancers (data extracted from TCGA tumor data)." (PMID 31992226, 2020). "Furthermore, the PI3K-AKT-dependent actions on motility may represent a generalized pathway in cancers with FAT1 overexpression, for example, as reported in high-grade gliomas whose invasiveness was dependent upon EGFR-AKT signaling." (PMID 40083689, 2025). "Thus, apart from FAT1-mediated modulation of immunosuppressive cytokine (TGF-β1) production in the glioma cells, the milieu provided by FAT1-expressing glioma cells may also influence TGF-β1 production in the monocytes present in the microenvironment." (PMID 35720420, 2022). "Moreover, in glioma cells in hypoxic conditions, an augmentation of the expression of Fat1 induce an increase of HIF-1 expression through growth factor receptors-Akt-mTOR pathway, suggesting that Fat1 controls the invasiveness of glioma cells through HIF-1 signaling." (PMID 35269788, 2022). "We have earlier shown that knock down of FAT1 led to increased PDCD4 level and repression of AP1 activity in glioma cells." (PMID 37476290, 2023). "Positive correlations of gene expression of FAT1 and TGF-β1/2 were observed in various cancers in TCGA, Glioma Longitudinal Analysis Consortium (GLASS), and Chinese Glioma Genome Atlas (CGGA) databases." (PMID 35720420, 2022). "We obtained a positive correlation of FAT1 expression with the expression of IL-10, PD-L1, and PD-L2 genes, the known surrogate markers of MDSCs, in primary and recurrent CGGA glioma cases." (PMID 35720420, 2022). "We have analyzed the role of FAT1 in modulating the expression of TGF-β1/2 in resected human gliomas, primary glioma cultures, and other cancer cell lines (U87MG, HepG2, Panc-1, and HeLa)." (PMID 35720420, 2022). "For example, FAT atypical cadherin 1 (FAT1) and the hepatocyte growth factor (HGF) pathway are both known molecular features of glioma pathogenesis." (PMID 29081735, 2017). "Similarly, expression correlation analysis in CGGA database yielded a positive correlation of FAT1 with TGF-β1 in primary glioma cases (r = 0.503, p < 0.01) and recurrent glioma cases (r = 0.865, p = 0.05) in mRNA_array_301 dataset." (PMID 35720420, 2022). "Therefore, we concluded that FAT1 regulates the secretion and/or expression of TGF-β1 and TGF-β2, which are well-known immunosuppressive cytokines, in glioma and other cancer cells." (PMID 35720420, 2022). "Hence, as suggested by the markers of MDSCs, increased expression of FAT1 in tumor cells may also correspond with increased MDSC infiltration, thereby contributing to another mode of immunosuppression in gliomas." (PMID 35720420, 2022).
glioma (continued). "To further investigate the possible molecular mechanism connecting FAT1 with regulation of TGF-β, we checked siFAT1-treated cells for changes in the level of miR-663a, which has previously been reported to posttranscriptionally regulate TGF-β1 in glioma and hepatocellular carcinoma cells." (PMID 35720420, 2022). "FAT1, a transmembrane protein, is a non-classical proto-cadherin that has a role in developmental processes as well as an oncogenic role in many human cancers like glioma, pancreatic cancer, leukemia, colon cancer, hepatocellular carcinoma (HCC) etc.." (PMID 31992226, 2020).
cervical carcinoma (15 papers, 2015 to 2025). A carcinoma arising from either the exocervical squamous epithelium or the endocervical glandular epithelium. "There are limited researches that reported the mutations of LRP1B and FAT1 genes in cervical cancer previously." (PMID 36076209, 2022). "In our current research, the missense mutation of FAT1 was identified in original cervical cancer, F2-PDX models and F3-PDX models." (PMID 36076209, 2022). "Therefore, the cervical cancer PDX models conserved the somatic mutations of FAT1 in original cervical cancer, and the mutated FAT1 gene could be utilized as the molecular target of new therapeutic regimens for cervical cancer patients." (PMID 36076209, 2022). "When studying the function of FAT1 in the cervical cancer cell line Hela, we noticed an increase in YAP and TAZ protein levels after knock-down of FAT1." (PMID 40478800, 2025). "Similar observations were also made in TIMER2.0 analysis where we had found a positive correlation between FAT1 expression and infiltration levels of tumor-promoting MDSCs in TCGA cases of cervical cancer, GBM, and pancreatic cancer." (PMID 35720420, 2022). "Another study in 15 cervical cancer patients from Hong Kong revealed frequently altered genes, including FAT1, ARID1A, ERBB2, and PIK3CA." (PMID 28390392, 2017). "FAT1 expression is lower in both esophageal squamous cell carcinoma and cervical cancer; notably, FAT1 knockdown promotes migration and invasion in esophageal squamous cell carcinoma cell lines and of HeLa and C33A cells, while FAT1 overexpression abrogates these cellular activities." (PMID 37371091, 2023). "Since HPV(+) head and neck cancers have driving mutations and cancer pathways in common with cervical cancers, including PIK3CA, FAT1, CASP8, PTEN, etc., comparing the subtypes of HPV(+) HNSCC with those of cervical cancer may reveal additional insights." (PMID 34072836, 2021). "The most frequent significantly mutated genes (SMGs) across the 430 cervical carcinomas were previously reported and included PIK3CA (27%), KMT2C (also known as MLL3) (19%), KMT2D (also known as MLL2) (13%), EP300 (12%), FBXW7 (12%), FAT1 (8%), and PTEN (8%)." (PMID 34620846, 2021). "Indeed, the PIK3CA gene is described as the top altered gene in cervical carcinoma along with the MTOR, KMT2D and FAT1 genes." (PMID 36010253, 2022). "We also observed in cases of cervical cancer [cervical and endocervical cancer (CESC); n = 306] that there is mostly an inverse correlation of FAT1 expression with infiltration levels of CD8+ T cells, CD4+ T cells, and dendritic cells and a positive correlation with infiltration of MDSCs." (PMID 35720420, 2022). "We mined TCGA cervical cancer datasets and found that besides YAP1 amplification, the upstream genes of the Hippo pathway, including MST1, LATS1/2, and FAT1/2/3/4, which negatively regulate YAP1 activity, were frequently deleted and/or mutated in cervical cancer patient samples." (PMID 30840887, 2019).
cervical carcinoma (continued). "The majority of those genes, excluding FAT1, which appeared as not applicable in GENT, were up- or downregulated in the tumor tissue samples of patients with cervical cancer." (PMID 25789025, 2015).
colorectal cancer (15 papers, 2016 to 2025). A primary or metastatic malignant neoplasm that affects the colon or rectum. "Mutated FAT1 and PKHD1 and altered Hippo pathway genes were found to be enriched in early-onset colorectal cancer." (PMID 36439454, 2022). "For example, FAT1 acts as both a tumor suppressor and oncogene and occurs in bladder cancer, head and neck cancers, breast and colorectal cancers." (PMID 33466343, 2021). "FhuD2‐mFAT1 is a C‐terminal fusion carrying the murine homolog of a surface‐exposed epitope of FAT1, a protein found overexpressed in colorectal cancer." (PMID 33643549, 2021). "Similarly, TGF-β2 was observed to be correlated with FAT1 in pancreatic cancer cases (r = 0.416, p = 9.61e-009), liver cancer cases (r = 0.342, p = 2.00e-011), and colorectal cancer cases (r = 0.167, p = 0.00004) of TCGA database." (PMID 35720420, 2022). "IRX5 promotes metastasis via RHOA signaling in colorectal cancer and regulates WNT/β-catenin pathways, which intersect with FAT1-mediated Hippo signaling." (PMID 40672387, 2025).